GFAP (glial fibrillary acidic protein)
Diseases named in the same sentence as GFAP in open-access papers (continued):
Sharing a sentence is not in itself a finding about the gene and the disease.
depression (continued). "Again, GFAP levels were identified to be significantly elevated in patients with unipolar depression compared with matched controls." (PMID 34021122, 2021). "This study is one of the first to measure S100B and GFAP in the CSF of patients with unipolar depression." (PMID 34021122, 2021). "For the first time, the current study produces evidence of astrocytic pathology in major depression in terms of increased GFAP signals based on CSF measurements." (PMID 34021122, 2021). "Several other studies have found lower GFAP levels and decreased numbers of astrocytes in different cerebral regions of patients suffering from depression compared to healthy controls." (PMID 34021122, 2021). "Patients with unipolar depression had significantly higher levels of GFAP than controls (733.22 pg/ml vs. 245.56 pg/ml, p < 0.001)." (PMID 34021122, 2021). "We found that Ori improved the reduction of GFAP expression in the hippocampus of the LPS-induced depression model." (PMID 35096901, 2021). "At present, GFAP has become a new target for the occurrence, development, and treatment of depression." (PMID 33192662, 2020). "Consistently, the current study also showed dynamic GFAP expression during the progression of the depression animal model." (PMID 31439031, 2019). "Very significant (up to 95%) decrease in GFAP expression and GFAP-positive astroglial profiles have been recently detected in the white matter of the ventral prefrontal cortex of subjects with major depression." (PMID 31379620, 2019). "Previous studies have shown a decrease in cortical astroglial numbers as reflected in a reduction in GFAP (an intermediate filament protein) stained cells in models of depression." (PMID 29907879, 2018). "Recently reduced expressions of GFAP and low density of GFAP+ cells has been reported in major depression, linking neuropsychiatric illnesses and astrocytes." (PMID 28546341, 2017). "Studies in postmortem human depressed subjects and animal models of depression demonstrate reduced immunoreactivity of GFAP (GFAP-IR) and GLT-1 protein expression." (PMID 28018190, 2016). "This is in agreement with findings from stress-induced depression and opposite to the increase in GFAP levels observed in the FSL rats compared to the SD rats." (PMID 27764188, 2016). "By contrast, neuropathological studies in specimens from major depression patients indicate reduction in hippocampal glial fibrillary acidic protein (GFAP)-positive astrocytes and of AQP4 and MT-I/II in the frontal cortex." (PMID 25889039, 2015). "In order to assess the contribution of neurons born in adolescence to the adult stress response and depression-related behavior, we transiently reduced cell proliferation either during adolescence, or during adulthood in GFAP-Tk mice." (PMID 25221485, 2014). "To investigate the contribution of exclusively adolescent-born neurons in the SGZ to depression-related circuitry, we have employed the GFAP-Tk mouse and created a valgancyclovir (VGCV) treatment regimen that transiently reduced neurogenesis from P28-P42." (PMID 25221485, 2014). "ACTB, CKB, NEFL, INA and GFAP had link to both schizophrenia and depression, while CTSD, HSPA8, NEFM and TUBA1A had link to schizophrenia." (PMID 23272063, 2012). "Last, the results of western blot further confirmed that administration of DSCG could attenuate LPS‐induced upregulation of iba1 and GFAP in the brain from depression model mice." (PMID 41556446, 2026). "Additionally, younger individuals with depression exhibit age‐dependent reductions in GFAP density and lower GFAP levels in the prefrontal cortex." (PMID 40855793, 2026). "An increase in GFAP expression in the PFC and striatum suggests that ketamine may counteract the loss of astrocytes observed in depression." (PMID 40097854, 2025).
depression (continued). "Similarly, when repeating analyses upon exclusion of late-life depression patients (n = 38), the associations of plasma VAMP2 [βs = −0.75 (95% CI −1.09 to −0.41)] and GFAP [βs = −0.35 (95% CI −0.57 to −0.12)] with SV2A PET SUVRcomp values were comparable." (PMID 40620474, 2025). "Additionally, increased GFAP concentrations have been observed in individuals with major depressive disorder, correlating with disease severity." (PMID 40838185, 2025). "Experimental depletion of GFAP+ astroglia in the prefrontal cortex of rodents induces anhedonia-like behaviors, while enhancing their activity reverses these behaviors, highlighting the critical role of cortical astroglia in depression." (PMID 40177583, 2025). "Peripheral GFAP was inversely associated with odds of depression (but not SI) within the first year of TBI with negative head CT scan." (PMID 40190352, 2025). "It remains unclear whether mild increases in plasma NfL and/or GFAP in bipolar disorder are related to the trait (bipolar disorder) or state (depression, mania or mixed state)." (PMID 40265626, 2025). "Astrogliosis is a well characterized feature of HIV-associated neuropathology and alterations in glial fibrillary acidic protein (GFAP), a marker of astrocyte reactivity, are associated with a variety of other brain disorders, including major depressive disorder (MDD)." (PMID 39175522, 2024). "We also tested whether the influence of changes in depression on the changes in GFAP levels differed according to sex, APOE4 status, or clinical diagnosis of the care recipient." (PMID 39297507, 2024). "In addition, structural affection was proved histomorphologically in different parts and layers of the hippocampus as a result of depression and was further proved by immunohistochemical reaction (GFAP)." (PMID 38315652, 2024). "For example, patients with major depressive disorder (MDD) exhibit distinct GFAP profiles, which may aid in the differential diagnosis of psychiatric conditions." (PMID 39796043, 2024). "However, a recent study found increased GFAP concentrations in the cerebral spinal fluid of patients with major depression compared to controls." (PMID 38990919, 2024). "Although there was an overall positive correlation between GFAP intensity and mitochondrial activity, the observation that decreases in mitochondrial activity were associated with higher depression symptoms absent changes in GFAP was somewhat unexpected." (PMID 39175522, 2024). "However, a decrease in the volume of hippocampal GFAP-immunoreactive astrocytes has been found in relation to depression and mood-disorders in human tissue and after posttraumatic stress disorder in rats." (PMID 36941713, 2023). "Severe clinical depression, anxiety, and schizophrenia all display diminished GFAP expression." (PMID 36818564, 2023). "Furthermore, a retrospective study found increased GFAP concentrations in the CSF of patients with unipolar depression compared to controls, indicative of astroglia injury." (PMID 37252156, 2023). "Compared with WT mice, the number of GFAP-positive cells in the hippocampus of CKO mice was significantly reduced after CSDS (p = 0.0021), indicating that astrocytic Kir6.1 deficiency promotes the loss of astrocytes in depression." (PMID 36185602, 2022). "In addition, a decrease in GFAP expression in astrocytes during depression can potentially lead to a decrease in the number of detected GFAP-positive cells." (PMID 35563389, 2022). "We tested the hypothesis that depression and apathy in PWH would be associated with higher levels of a biomarker of astrocyte activation, glial fibrillary acidic protein (GFAP), in cerebrospinal fluid (CSF)." (PMID 37205974, 2022).
depression (continued). "Neural factors like GFAP and NE levels were firmly related to patients' depression." (PMID 35401732, 2022). "Several variables were significantly related to depression parameters and GFAP levels." (PMID 37205974, 2022). "Expression of glial fibrillary acidic protein (GFAP) is upregulated in activated astrocytes, and cerebrospinal fluid (CSF) levels of GFAP, a marker of astrocyte activation, are increased in people with depression." (PMID 37205974, 2022). "Similarly, astrocytic atrophy and decreased expression of the astrocyte biomarker GFAP have been documented in both animal depression models and autopsy specimens of depressed patients." (PMID 34611141, 2021). "This suggests that prefrontal cortex white matter may have a particularly strong subregional heterogeneity for depression-related changes in GFAP-IR astrocyte density." (PMID 33613346, 2021). "Therefore, the aim of the current study was to examine GFAP and S100B levels in the CSF of patients with major depression to better understand their role in affective disorders." (PMID 34021122, 2021). "In conclusion, higher GFAP levels in patients with depression may be indicative of altered microglia activity, especially in astrocytes, in patients with unipolar depression." (PMID 34021122, 2021). "Numerous other studies have associated astrocyte dysfunction with the pathogenesis of major depressive disorders, including the notion that the density of GFAP-immunoreactive astrocytes was decreased in the hippocampus of patients suffering from major depressive disorders." (PMID 35011927, 2021). "The product of the GFAP gene is one of the major intermediate filament proteins of mature astrocytes and a specific marker for astrocytes known to be involved in the pathogenesis of major depression (MDD) and schizophrenia." (PMID 34552157, 2021). "Astrocytes IR to vimentin (VIM) display different regional densities than GFAP-IR astrocytes in the healthy brain, and so may be differently altered in depression and suicide." (PMID 33613346, 2021). "Given that GFAP is elevated in the CSF of patients with major depression, it may serve as an additional state or trait biomarker in depression." (PMID 34021122, 2021). "The expression levels of miRNAs were detected by qRT-PCR, and the expression levels of Wnt2, depression-impacted proteins (GFAP, BDNF, CREB), brain neurotransmitters (5-HT, NE, DA) and apoptosis-related proteins (Bax and Bcl-2) were evaluated by qRT-PCR and western blot." (PMID 33927285, 2021). "Recently, progressive multiple sclerosis model caused depression- and anxiety-like behaviors, which has been found simultaneously upregulation of IL-17 and GFAP in the hippocampus but not prefrontal cortex." (PMID 34565419, 2021). "However, the results of previous studies to date tend to indicate a transdiagnostic phenomenon; thus, it is necessary to evaluate GFAP in patients with depression in combination with other alterations, such as altered cytokine levels." (PMID 34021122, 2021). "However, with the over-activation of the Glu system, the astrocyte (GFAP) content of hippocampal is reduced and neuron injury, eventually leading to the occurrence of depression." (PMID 33192662, 2020). "Other animal experiments have also found that different patterns of stimulation in the depression model, the expression in GFAP, and the number of positive cells of GFAP were found to be down-regulated in key brain regions such as the cortex-marginal system and hippocampus." (PMID 33192662, 2020). "A decrease in expression of GFAP, a marker of astrocytes, was observed in depression patients." (PMID 31312123, 2019). "The expression of glial fibrillary acidic protein (GFAP), the marker of astroglial reactivity, which reveals the cytoskeleton of astrocytes, is generally suppressed in brain samples from young or adult subjects with depression and BD." (PMID 31379620, 2019).
depression (continued). "Several studies have shown a decrease in GFAP expression in cortical astroglial cells in postmortem tissue of depressed suicides and in animal models of depression, leading authors to conclude that there is a decrease in the total number of cortical astroglial cells in depressive-like phenotypes." (PMID 29907879, 2018). "In conclusion, these results reveal that chronic administration of XYS elicits antidepressant-like effects in a mouse model of depression and may normalize glial fibrillary acidic protein expression in the hippocampi of mice with CUMS." (PMID 28348623, 2017). "Anxiety-like behavior (light-dark test), depressive-like behavior (forced swim test), plasmatic levels of the brain-derived neurotrophic factor (BDNF, depression biomarker), and central glial fibrillary acidic protein (GFAP) expression (an astrocyte biomarker) were also evaluated." (PMID 28056040, 2017). "Similar results were reported in a rat model of depression, where GFAP expression was reduced." (PMID 27579183, 2016). "Similarly, in studies of the prefrontal cortex of patients with schizophrenia and MDD (major depressive disorder), reductions in GS and GFAP expression have been reported." (PMID 24059854, 2013). "In addition to addressing the limitations detailed above, future research may also benefit from incorporating biofluid measures of GFAP, a measure of astrocytic reactivity, and VEGF, which has been linked to rTMS efficacy in clinical trials for depression." (PMID 40746364, 2025). "Disruption of the BBB allows pro-inflammatory molecules to invade the central nervous system (CNS), activate microglia, and drive neuroinflammation, inducing or exacerbating depression, which may be manifested as a sustained elevation of glial fibrillary acidic protein (GFAP) levels." (PMID 41301929, 2025). "It is currently unknown if acute blood concentrations of GFAP are associated with post-TBI depression and/or suicidal ideation (SI) but identifying objective markers of depression and suicidality could improve clinical decision making for patients who may need long-term monitoring after TBI." (PMID 40190352, 2025). "In line with this hypothesis, an increase in plasma levels of markers of astrocytic activation, such as glial fibrillary acidic protein (GFAP) and S100β, are here shown to be significantly increased in patients with treatment-resistant depression when compared to healthy individuals." (PMID 38474387, 2024). "Therefore, serum GFAP levels might be a useful biomarker candidate to distinguish and monitor the severity of major depressive disorder." (PMID 37252156, 2023). "However, GFAP in prefrontal cortex is found to be decreased in depressive disorder." (PMID 36550591, 2023). "Additionally, glial fibrillary acidic protein (GFAP), one of the astrocyte-specific biomarkers, is reduced in depression-associated brain regions including the prefrontal cortex, cingulate cortex, hippocampus, amygdala, locus coeruleus, cerebellum, thalamus, and caudate nuclei." (PMID 34025481, 2021). "Besides, there is evidence that only by inhibiting the number of GFAP-positive glial cells is sufficient to induce depressive phase behavior in rats, classic anti-depression drugs such as fluoxetine can act as antidepressants to improve this pathological change and depressive-like behaviour." (PMID 33192662, 2020). "Furthermore, changes in the expression of glia-derived genes and glial fibrillary acidic protein (GFAP) in depression and other psychiatric illnesses indicate that suicide-related molecular alterations may not be restricted to neurons." (PMID 23272063, 2012). "Secondly, the increasing number of GFAP+ (astrocyte) cells in the DG, CA1, and cortex of depression model mice was also ameliorated by administration of DSCG." (PMID 41556446, 2026). "Higher levels of plasma GFAP have been demonstrated both among APOE ε4 carriers and in individuals with depression." (PMID 41476029, 2026).
depression (continued). "Elevated plasma levels of glial fibrillary acidic protein (GFAP) and S100β, markers of astrocytic activation, have been observed in patients with treatment-resistant depression compared to healthy individuals." (PMID 40573262, 2025). "Nicotine withdrawal significantly elevated anxiety-, depression-, and anhedonia-like behaviors, increased oxidative stress, and upregulated MAO-A activity and GFAP expression, indicating neuroinflammatory effects." (PMID 40780966, 2025). "It has been shown that individuals with depression have larger numbers of GFAP and AQP4/GFAP-positive EVs in the blood than healthy controls, suggesting increased leakage of astrocyte-derived EVs through the blood–brain barrier." (PMID 38474112, 2024). "In fact, increases in GFAP have been detected in the blood of people with neurologic or psychiatric disorders, including PWH with depression." (PMID 39175522, 2024). "The results showed that infusion of L-AAA significantly decreased the expression of astrocytic glial fibrillary acidic protein (GFAP), which was accompanied by increased depression and anxiety-like behaviors." (PMID 38999797, 2024). "Several components critical to astrocyte function were found to downregulate in studies exploring the abnormal gene expression in the brain tissue of patients with depression including SLC1A3, GLUL, GFAP, and S100 calcium-binding protein." (PMID 38023826, 2023). "In rodent depression models or postmortem patients with MDD patients, the expression of GFAP reduced in the Hip and prefrontal cortex as compared to controls." (PMID 35130906, 2022). "The mean±SD log10 CSF GFAP level was 3.47±0.0781pg/mL, and the mean BDI-II score was 12.2±9.84, with 39.2% having a BDI-II>13, reflecting at least mild depression." (PMID 37205974, 2022). "MiR-133b augmentation was associated with decreased apoptosis, repressed inflammatory reaction, and increased expression of GFAP, BDNF and neurotransmitters in hippocampal tissues of depression rats." (PMID 34829888, 2021). "The previous review summarized that the expression of the glial fibrillary acidic protein (GFAP) and representative astrocyte related proteins was significantly decreased in subjects with major depressive disorders." (PMID 33628324, 2021). "In fact, the two most referenced biomarkers of SCZ, namely Fructose-bisphosphate aldolase C (ALDOC) and Glial fibrillary acidic protein (GFAP), are also altered in major depression and bipolar disorder." (PMID 33668817, 2021). "GFAP fluorescence is significantly reduced in the hippocampal CA1 and CA2 regions in patients with depression." (PMID 33109198, 2020). "This study demonstrates that GFAP-positive astrocyte-specific deletion of GLT1 reduced anxiety- and depression-like behaviors using a comprehensive array of behavioral tests including EPM, TST and FST." (PMID 32390810, 2020). "Since previous studies showed a correlation between astrocytic degeneration in the mPFC and depression-like behavioral changes, we examined the effects of L-AAA and Lu AA33810 on the GFAP protein level in the rat PFC." (PMID 27975125, 2017). "Collectively, these results indicate that while attenuation of hippocampal cellular senescence via vitamin C is sufficient to alleviate depression‐like behavior, it does not restore memory function or astrocytic integrity as reflected by GFAP expression." (PMID 40855793, 2026). "Participants with depression had significantly lower GFAP compared with participants without depression overall (median = 149.9 pg/mL versus 306.9 pg/mL, P < 0.001) and CT-negative high risk and CT-negative low risk subgroups." (PMID 40190352, 2025). "Significant differences between MCI with awareness vs MCI with anosognosia in clinical features were HADS-Depression (t=−3.2, df=98, p=0.001), and HADS-Anxiety (t=−2.6, df=98, p=0.009) scores, while differences in biomarkers were limited to GFAP (t=−2.2, df=90, p=0.033)." (PMID 40166560, 2025).